MPO (myeloperoxidase)
Diseases named in the same sentence as MPO in open-access papers (continued):
Sharing a sentence is not in itself a finding about the gene and the disease.
atrial fibrillation (24 papers, 2011 to 2025). A disorder characterized by an electrocardiographic finding of a supraventricular arrhythmia characterized by the replacement of consistent P waves by rapid oscillations or fibrillatory waves that vary in size, shape and timing and are accompanied by an irregular ventricular response. "In an angiotensin II-induced inflammatory mouse model of atrial fibrillation, MPO-deficient mice exhibited a signification reduction in atrial tissue levels of HOCl, active MMPs, and atrial fibrosis compared to wild-type mice." (PMID 39061857, 2024). "Mpo−/− mice showed markedly reduced atrial fibrosis and were almost completely protected from the increased vulnerability to atrial fibrillation caused by AngII administration, and both of these effects were dose‐dependently reversed upon restitution of MPO." (PMID 33460291, 2020). "Furthermore, upon cardiac electrophysical stimulation, the MPO-deficient mice exhibited reduced atrial fibrillation, which was reversed by chronic intravascular infusion of human neutrophil-derived MPO." (PMID 39061857, 2024). "Based on the current results, the MPO cytokines in pericardial fluid are increased and superimposed on the susceptible atrial substrate, making the atrium vulnerable to the induction and maintenance of atrial fibrillation." (PMID 36498593, 2022). "Under right atrial electrophysiological stimulation, MPO-deficient mice were protected from atrial fibrillation, which was reversed when MPO was restored; this finding indicated that MPO is a key prerequisite for myocardial remodeling, leading to increased susceptibility to atrial fibrillation." (PMID 33680285, 2021). "It is tempting to speculate that this cytokine receptor, which regulates chemotaxis and formation of lymph nodes, may be involved in the production of myeloperoxidase in the left atrium, which has recently been linked to development of atrial fibrillation and atrial fibrosis." (PMID 22039477, 2011). "Atrial fibrillation patients also have increased circulating and atrial tissue levels of MPO and elevated atrial levels of 3-chlorotyrosine, which indicates MPO-mediated oxidative tissue damage." (PMID 39061857, 2024). "A recent MR study genetically determined that elevated plasma MPO levels are causally associated with increased risks of ischemic stroke, cardioembolic stroke (CES), heart failure (HF), and atrial fibrillation (AF)." (PMID 38576857, 2024). "Myeloperoxidase (MPO), released by activated neutrophils, is significantly increased in atrial fibrillation (AF)." (PMID 37719981, 2023). "Myeloperoxidase, released from activated neutrophils, modulates vascular inflammation and NO bioavailability, linking it to HF post-ischemic injury, atrial structural remodeling, and atrial fibrillation (AF) risk." (PMID 37900404, 2023). "Experimental and clinical evidence revealed that neutrophil MPO is involved in atrial fibrillation pathogenesis." (PMID 33680285, 2021). "Accumulating evidence suggests that myeloperoxidase (MPO) is involved in atrial remodeling of atrial fibrillation (AF)." (PMID 27342818, 2016). "We have reported recently that MPO, stored in primary granules of PMN and released by the cells upon activation, links atrial fibrosis and the susceptibility for atrial fibrillation." (PMID 24558493, 2014). "MPO may play a role in the progression of atrial fibrillation and further involved in AF recurrence after catheter ablation." (PMID 37719981, 2023). "A key mechanistic link by which MPO contributes to atrial fibrillation seems to be atrial fibrosis." (PMID 33460291, 2020). "Furthermore, MPO may be involved in thepathophysiology of atrial fibrillation through atrial accumulation of MPO andconsequent increase in fibrosis." (PMID 39077419, 2023). "In the studies of pre-AF, it has been found that humans with atrial fibrillation had higher plasma concentrations of MPO and a larger MPO burden in right atrial tissue as compared to individuals devoid of atrial fibrillation." (PMID 36498593, 2022).
atrial fibrillation (continued). "Thus, MPO acts as a major downstream mediator of atrial fibrosis and atrial fibrillation." (PMID 33460291, 2020). "MPO is a crucial prerequisite for structural remodeling of the myocardium, leading to an increased vulnerability to preoperational atrial fibrillation (pre-AF)." (PMID 36498593, 2022). "Previous studies shown that myeloperoxidase (MPO) level is higher in patients with atrial fibrillation (AF); however, no genetic evidence between MPO and AF risk in human population was observed." (PMID 33460291, 2020). "Procedures, such as catheter ablation, trigger an immune response, where neutrophils are considered the primary source of reactive oxygen species (ROS) and myeloperoxidase (MPO) and have been attributed to both atrial fibrillation recurrence and pericarditis due to inflammation." (PMID 39156919, 2024). "MPO is a crucial regulatory switch modulating matrix metalloproteinases (MMPs) activity, and MMPs were key effectors of extracellular matrix (ECM) turnover and remodelling in atrial fibrillation." (PMID 33460291, 2020).
Crohn disease (24 papers, 2009 to 2026). A gastrointestinal disorder characterized by chronic inflammation involving all layers of the intestinal wall, noncaseating granulomas affecting the intestinal wall and regional lymph nodes, and transmural fibrosis. "MPO-ANCA is reportedly useful for differentiating UC from Crohn’s disease because UC cases in Western countries are often positive for MPO-ANCA." (PMID 34425765, 2021). "The result of ELISA revealed that the expression of MPO in colonic mucosae from the active Crohn’s disease patients who had dietary fiber in their food or enteral nutrition (ac-DF and re-DF) was significantly higher than that in the other groups." (PMID 26140540, 2015). "Similarly, in Crohn’s disease, characterized by intestinal inflammation and immune dysregulation, UVB-induced MPO activity may intensify oxidative stress, underlining the need to limit UVB exposure in such contexts." (PMID 40895555, 2025). "Primary outcomes were the absolute difference (Δd7-d0) in; Crohn's Disease Activity Index (CDAI) score and fecal myeloperoxidase (MPO)." (PMID 42238434, 2026). "If the antioxidant response is not sufficient, as in Crohn's disease where an overall increase in ROS/RNS results because of an excessive accumulation of MPO in the tissue coupled with a decrease in hydroxyl radical scavengers, the balance is shifted." (PMID 19912645, 2009).
anemia (23 papers, 2013 to 2026). A reduction in the number of red blood cells, the amount of hemoglobin, and/or the volume of packed red blood cells. "A higher average MPO concentration was also associated with a greater risk of anemia, and this is of interest because MPO is an iron-containing protein released from neutrophils in response to mucosal injury, and directly indicates loss of iron from the body." (PMID 31565748, 2019). "Laboratory investigations found anemia, rapidly progressive renal impairment, and positive anti-MPO perinuclear anti-neutrophil cytoplasmic antibodies (p-ANCA) at high titers, supporting a diagnosis of MPA." (PMID 40688904, 2025). "Patience presented with pyrexia, anaemia and increased levels of serum MPO levels had increased likelihood of malaria infection." (PMID 36658587, 2023). "A greater risk of anemia was associated with greater intestinal permeability [LMZ: 1.15 (1.01, 1.31)] and inflammation [higher MPO: 1.16 (1.01, 1.34)]." (PMID 31565748, 2019). "A greater risk of anemia was associated with LMZ [1.15 (95% CI: 1.01, 1.31)] and MPO [1.16 (1.01, 1.34)]." (PMID 31565748, 2019). "Taken together, NAC supplementation and/or MPO inhibition improves endothelial function in anemia." (PMID 37234375, 2023). "Recent studies demonstrated that higher plasma NGAL levels were associated with presence of anemia independent of estimated glomerular filtration rate, plasma high-sensitivity C-reactive protein, and myeloperoxidase levels." (PMID 25013661, 2013). "Notable findings included leukocytosis (17,000/μL), normocytic anemia, thrombocytosis (672,000/μL), highly elevated inflammatory markers (CRP 145 mg/L, ESR 120 mm/h), and strongly positive MPO-ANCA (>134 U/mL)." (PMID 41515620, 2026). "Laboratory results demonstrated leukocytosis (17,000/μL), normocytic anemia (hemoglobin 10.1 g/dL), thrombocytosis (672,000/μL), elevated inflammatory markers (CRP 145 mg/L, ESR 120 mm/h), and strongly positive perinuclear MPO-ANCA > 134 U/mL." (PMID 41515620, 2026). "In light of persistent vasculitis activity, manifested by pulmonary infiltrates and elevated MPO-ANCA titers, and refractory anemia unresponsive to prior therapy, RTX (500 mg every two weeks) was initiated after ruling out contraindications." (PMID 40901468, 2025). "The risk factors that have been classically associated with AAV development in patients with preexisting ILD include elevated inflammatory markers, anemia, radiological UIP pattern, older age, fever, anti-MPO positivity, or higher serum ANCA levels." (PMID 39797313, 2025). "The degree of anemia in idiopathic double-positive AAV (74.15 ± 40.10), reflected by the level of hemoglobin, was comparable to MPO-AAV (82.68 ± 20.04) and more severe than PR3-AAV (95.49 ± 23.47)." (PMID 38564029, 2024). "Of the two patients who were positive for p-ANCA/MPO and c-ANCA/PR3, only pulmonary lesion and anemia were observed." (PMID 25923706, 2015). "Here, we present the case of a patient with myeloperoxidase-specific antineutrophil cytoplasmic antibody (MPO-ANCA) positive AAV who suffered from severe, transfusion-dependent anemia and advanced tubulointerstitial atrophy that was unresponsive to standard therapy." (PMID 40901468, 2025). "We observed significant positive correlations of the total PR3 blood pool with clinical markers of systemic inflammation, such as CRP; anemia, such as hemoglobin; and kidney injury, such as creatinine and erythrocyturia, in patients with PR3-AAV but not in patients with MPO-AAV." (PMID 36125911, 2022).
endometritis (23 papers, 2017 to 2025). An acute or chronic, usually bacterial infectious process affecting the endometrium. "The results demonstrated that the expression levels of ELA2 and MPO, two critical markers associated with neutrophil activation and NETs formation, were markedly elevated in the WT endometritis group compared to STING-deficient mice." (PMID 41583494, 2025). "Myeloperoxidase (MPO), as a marker of neutrophil activation, has been associated with equine endometritis." (PMID 36766264, 2023). "Some studies have focused on MPO and its implications in pathological conditions of the endometrium, such as endometritis and endometrosis, which are a major cause of infertility in the mare that adversely impact the horse breeding industry." (PMID 36766264, 2023). "Another study performed on endometritis-susceptible mares at foal heat found that neutrophil activity increased together with MDA and fibrinogen plasma levels, whereas myeloperoxidase (MPO) activity was slightly lower in endometritis-susceptible than in -resistant mares." (PMID 36670793, 2023). "In contrast, STING-deficient mice exhibited diminished MPO levels in response to LPS stimulation, suggesting that STING deficiency impairs neutrophil recruitment and activation in the context of endometritis." (PMID 41583494, 2025). "Previous studies have also shown that alpinetin attenuates inflammation by reducing MPO activity in a septic mouse model and in mice with lipopolysaccharide (LPS)-induced endometritis." (PMID 41373489, 2025). "In this study, using LPS-induced murine endometritis models in wild-type and STING-deficient mice, we demonstrated that STING deficiency significantly suppressed myeloperoxidase activity, and diminished NETs formation." (PMID 41583494, 2025). "✧Prevented the endometritis via inhibition of MPO, NF-Κb, TNF-α, and IL-1β.✧Enhanced the expressions of Nrf2 and HO-1 levels and suppressed the MDA content." (PMID 39408650, 2024). "In mares, a previous study found a significant increase in MPO levels in uterine fluid samples in cytologically endometritis-positive subjects analyzed by ELISA." (PMID 36670793, 2023). "In vivo experimentations showed that fisetin lessened inflammatory damage and MPO activity in LPS-stimulated mouse endometritis." (PMID 36982152, 2023). "Myeloperoxidase (MPO) is an enzyme mainly contained in inflammatory cells and indeed associated with equine endometritis." (PMID 36766264, 2023). "Neutrophil infiltration is a typical characteristic of endometritis, with increased levels of myeloperoxidase (MPO) commonly used to suggest neutrophil infiltration." (PMID 35565576, 2022). "This study demonstrates that Cl-amidine can alleviate LPS-induced rat endometritis by inhibiting NETs formation, blocking histone citrullination in the nucleus of neutrophils with reduced production of MPO." (PMID 35565576, 2022). "In endometritis-susceptible mares, following insemination at the foaling heat, neutrophil activity increased together with MDA and fibrinogen plasma levels, whereas MPO was slightly lower in susceptible than in resistant mares." (PMID 36139263, 2022). "We found that challenge with LPS increased uterine MPO activity by 41%, while Cl-amidine reduced LPS-provoked endometritis levels of MPO by 25%." (PMID 35565576, 2022). "We also found that IAld, indole, and IPA treatment alleviated E. coli-induced endometritis, which was shown by improved uterine inflammatory injury and reduced inflammatory markers including MPO activity, TNF-α, and IL-1β compared with the E. coli group." (PMID 35727038, 2022). "It suggested that GnRb1 effectively alleviated endometritis by suppressing uterine edema and MPO activity." (PMID 34885671, 2021). "The results of in vivo experiments have indicated that thymol alleviates inflammatory injury and decreases MPO activity in LPS-induced mouse endometritis." (PMID 28223539, 2017).
endometritis (continued). "However, pretreatment of luteolin significantly reduced MPO activity in S. aureus–induced endometritis mice." (PMID 38169293, 2024). "Intraluminal accumulation of MPO from successive cycles and/or previous endometritis may contribute to the intraluminal MPO and may explain individual differences in MPO (RT) concentrations observed between mares." (PMID 36766264, 2023). "However, pretreatment with C. butyricum inhibited MPO activity in a dose-dependent manner in E. coli-induced endometritis mice." (PMID 36321897, 2022). "The effect of IFN-τ on MPO activity was examined in mice with S. aureus-induced endometritis." (PMID 28331850, 2017). "Similarly, immunofluorescence staining with MPO-expressing neutrophil infiltration was scarce in controls but markedly increased in chronic endometritis uteri, further corroborating aberrant neutrophil activation and NETs deposition in endometritis progression." (PMID 41583494, 2025). "The results showed that S. aureus significantly increased the levels of MPO, TNF‐α, IL‐1β and IL‐6 in uterine tissue, and increased the expression of p‐p65 and p‐IκBα proteins in uterine tissue to induce endometritis in mice (p < 0.05)." (PMID 39042561, 2024). "Moreover, in a mouse model of LPS-induced endometritis, melatonin treatment repressed the expression of pro-inflammatory cytokines by ELISA and qRT-PCR, alleviated pathological changes by hematoxylin–eosin staining (H&E), and inhibited myeloperoxidase (MPO) activity." (PMID 37570258, 2023). "Siquera and colleagues found that cows with endometritis showed an increase in serum levels of MDA, and hence, lipid peroxidation, as well as a higher MPO activity, used as an inflammatory marker and related to neutrophil activation." (PMID 36139263, 2022). "Second, we focused on the protective effects of AS IV against LPS-induced endometritis concerning the aspects of histopathological changes, inflammatory cytokine levels (IL-1β and TNF-α), concentration of NO, and myeloperoxidase activity in the uterus." (PMID 30669661, 2019). "Previously, some mares with no sign of endometritis have been shown to have high concentrations of total MPO in the uterine lumen, similar to those presenting inflammation." (PMID 36766264, 2023). "In fact, mares diagnosed with endometritis present higher concentrations of MPO than those where no inflammation was observed." (PMID 36766264, 2023). "High concentrations of MPO in uterine lavage of mares was already related with endometritis, even though this was not demonstrated in cows with endometritis." (PMID 33467081, 2021). "Although this should be confirmed by transcriptomic and proteomic approach, such as in situ hybridization analysis, these results suggest that the endometrium may be a source of MPO in absence of endometritis." (PMID 36766264, 2023). "Total and active MPO concentrations were determined, by ELISA and SIEFED assay, respectively, in low-volume lavages from mares in estrus (n = 26), diestrus (n = 18) and anestrus (n = 8) in absence of endometritis." (PMID 36766264, 2023).